IL2 (interleukin 2)
Diseases named in the same sentence as IL2 in open-access papers (continued):
Sharing a sentence is not in itself a finding about the gene and the disease.
diabetes (continued). "Previous results and the current study showed that low dose IL-2 only partially protect mice from diabetes." (PMID 38424350, 2024). "When CD80 was co-expressed with TNF-α or IL-2, a large proportion of mice developed severe pancreatitis and diabetes mellitus." (PMID 39777226, 2024). "Earlier work in NOD mice has shown that low dose IL-2 has a partial protective effect against diabetes." (PMID 38424350, 2024). "Low dose IL-2 together with an immunosuppressant rapamycin was found to prevent diabetes in NOD mice." (PMID 38424350, 2024). "On the other hand, low dose IL-2 prevented diabetes in NOD mice and partially induced diabetes remission." (PMID 38424350, 2024). "In other mouse models of autoimmune diseases, such as C57BL/6 mice, CD4+ CD25+ Tregs are also induced by recombinant IL-2, thus preventing the progression of diabetes." (PMID 36776877, 2023). "These markers remained significantly associated with AF after adjusting for age, sex, hypertension, and diabetes mellitus (Model 1), with the exception of IL-2." (PMID 36834735, 2023). "Decreased IL-2 signaling has been reported in patients with Diabetes mellitus due to poor phosphorylation of STAT-5 in the IL-2 signaling cascade as well as single nucleotide polymorphisms (SNP), which can eventually result in aberrant wound healing." (PMID 37575261, 2023). "At lower doses than WT IL-2, this fusion protein has been shown to decrease the occurrence of diabetes in NOD mice and decreased symptom severity in SLE mouse models." (PMID 36399073, 2023). "Functionally, the IL-2/mab complexes displayed potent suppressive activity as measured in murine models of diabetes, EAE and xenogeneic GVHD." (PMID 36675265, 2023). "Total amounts of TGF-β, MIP-1α, IL-6, IL-2, and IL-17 were significantly increased in the periodontally healthy sites of diabetes patients (p < 0.05), compared to those of the controls." (PMID 37835794, 2023). "Earlier studies have shown that, although regulatory T cells (Tregs) appear to be normal in number, individuals with diabetes have some functional defects, which include a reduced capacity to respond to IL-2." (PMID 34709423, 2022). "Ultra-low interleukin-2 (IL-2) treatment reversed diabetes development in mice, however, in humans this effect was only temporary and led to expansion of CD8 cells." (PMID 35903316, 2022). "Cold ischemia time (CIT), donor history of diabetes mellitus, donor interleukin-2 (IL-2) level and donor terminal creatinine level constitute the prediction system." (PMID 35971094, 2022). "Administration of rapamycin, an mTORc1-blocking drug inhibiting effector T cells but not Foxp3+ Tregs, with CD28 costimulatory molecule blockade or with IL-2/anti-IL-2 immune complexes demonstrated convincing capacities to delay diabetes in NOD mice." (PMID 35455658, 2022). "Control NOD mice had a 60% rate of diabetes occurrence, while those treated with IL-2 were fully protected from diabetes." (PMID 35917175, 2022). "Acceleration of diabetes onset resonates with previous reports that IL-2 and untethered IL-2/antibody complexes can exacerbate disease pathogenesis, highlighting the safety, selectivity, and efficacy advantages for our IC." (PMID 36261022, 2022). "In contrast, low doses of IL-2 have been used to treat autoimmune conditions, such as diabetes, ulcerative colitis, graft-versus-host disease (GVHD), and allograft rejection." (PMID 36261022, 2022). "The DGF prediction model was calculated using the formula (-9.6319 + 0.368 × CIT + 1.789 × donor history of diabetes mellitus + 0.047 × donor IL-2 level + 0.749 × donor terminal creatinine level)." (PMID 35971094, 2022). "Animal experiments have demonstrated that low-doses of IL-2 can enhance the proportion of Treg cells in islet tissues, thereby reducing the incidence of diabetes in mice." (PMID 36244973, 2022). "For instance, low-dose IL-2 (ld-IL-2) prevents and reverses diabetes in the spontaneous NOD mouse model." (PMID 34324441, 2021).
diabetes (continued). "In NOD mice, low-dose IL-2 prevents clinical onset and reverses diabetes via an expanded pool of Foxp3+ Treg in the islets and draining pancreatic lymph nodes." (PMID 30166987, 2018). "In agreement with other reports showing that low-dose IL-2 treatment protects NOD mice from diabetes development, insulitis was significantly reduced in the IL-2c treated mice (p < 0.001)." (PMID 29454391, 2018). "A second clinical trial, conducted by Diabetes TrialNet and the Immune Tolerance Network, used higher doses of IL-2 in combination with the inhibitor of the mammalian target of rapamycin (mTOR), rapamycin." (PMID 28770318, 2017). "For example, OK-432 (a streptococcal preparation), a potent activator of both macrophages and killer T cells and an enhancer of IL-2 production, inhibited development of diabetes in all the treated animals over 24-week observation period compared to control." (PMID 28824543, 2017). "Our group found that through NF-κB inhibition, P. hepiali suppressed the release of proinflammatory cytokines, including tumor necrosis factor alpha, IL-2, IL-6 and IL-10, in a rat model of diabetes induced by a high-fat diet and STZ." (PMID 28662169, 2017). "Substantially lowering the IL-2 complex dose, which was effective in preventing diabetes in pre-diabetic NOD mice, still was unable to promote BM engraftment." (PMID 26731275, 2016). "Although research has focused on the role of IL-2 on T cells and specifically Treg numbers in diabetes, IL-2 also affects DC development." (PMID 26124756, 2015). "NOD mice treated with low-dose IL-2 showed increase in Tregs and reversal or prevention of diabetes." (PMID 26834735, 2015). "In contrast to beneficial low-dose IL-2 therapy (2.5 × 104 IU/day), higher IL-2 doses (2.5–5 × 105 IU/day) did not prevent T1D in some mice and even dramatically accelerated onset of diabetes despite local and systemic Treg improvement." (PMID 25322151, 2014). "NOD mice express less IL-2 than diabetes resistant mouse strains, and low dose IL-2 administered at the onset of type 1 diabetes can reverse established disease in NOD mice." (PMID 24586872, 2014). "Control or Ab/IL-2 treated pancreata were processed for immunofluorescence staining with insulin and Ki67, within the first or second week after diabetes onset." (PMID 24205242, 2013). "NOD mice congenic for the Idd3 locus have a strongly reduced incidence of diabetes and candidate genes include IL-2 and IL-21." (PMID 23850635, 2013). "Recently, it has been shown that low-dose IL-2 administration at diabetes onset can induce long-lasting remission in the treated mice." (PMID 21647403, 2011). "Recently, it has been shown that the administration of low doses of IL-2 at the onset of diabetes can induce a long-lasting remission in NOD mice." (PMID 21647403, 2011). "We also examined the ability of polyclonal CD4+CD25+ T cells expanded by anti-CD3 plus IL-2 for inhibition of diabetes transfer." (PMID 19759824, 2009). "Persistence ofsignificant difference between the cases with IDDM monitored for along time and controls in terms of IL-1β, IL-2, IL-6, andTNF-α supports continuous activation during the latestages of diabetes." (PMID 16864906, 2006). "In all stages of diabetes higher levels of IL-1β andTNF- α and lower levels of IL-2 and IL-6 were detected." (PMID 16864906, 2006). "It would be interesting to consider the direct effect of low-dose IL-2 on glucose metabolism and whether engineering of IL-2 to improve its action will ameliorate diabetes and its complications, including diabetic retinopathy." (PMID 40133487, 2025). "Similarly, in the retina of diabetic mice, low-dose IL-2 increased Tregs and reduced CD8+ T cells compared with untreated diabetic mice (untreated diabetes: 4.65 ± 0.58 vs diabetes + low-dose IL-2: 3.00 ± 0.81 cells per field, p<0.01)." (PMID 40133487, 2025). "A decrease in IL-12 is probably responsible for reduced IL-2 in patients with diabetes." (PMID 38731110, 2024).
diabetes (continued). "Either Tregs might be directly equipped with IL-2 signals or employing low-dose IL-2 has been effective in enhancing endogenous Tregs, leading to diabetes prevention and reversal in the NOD mouse model." (PMID 38507159, 2024). "Altogether, our data illustrate that low dose IL-2 treatment did not alter Treg and Breg cell responses but reduced the response of antigen presenting cells, and could be the reason why low dose IL-2 only provided partial protection against diabetes." (PMID 38424350, 2024). "Furthermore, changes in microbiota induced by the antibiotics treatment resulted in the higher incidence of MLDS-induced diabetes in C57BL/6 mice, which was associated with the reduction in IL-2-expressing ILC3 and Treg proportions in the SILP." (PMID 37110604, 2023). "Lower serum IL-2 in mice with a higher incidence of MLDS-induced diabetes when treated with antibiotics in our study are in line with the study that demonstrated marked decrease in serum IL-2 levels in patients with T1D at the time of diagnosis and in long-standing T1D." (PMID 37110604, 2023). "We next investigated the serum concentration of IL-2 in C56BL/6 mice with MLDS-induced diabetes." (PMID 37110604, 2023). "Chronic toxoplasmosis was suggested to play a role in the pathogenesis of type 2 diabetes mellitus (T2D) due to the correlation between the state of insulin resistance in T2D and the elevated levels of circulating inflammatory cytokines including IL-2,4; IL-6,5; IL-12,6; TNF; and IFN." (PMID 36672526, 2022). "Deployment of an IL-2-based therapy in a mouse model of immune checkpoint inhibitor-induced diabetes showed that F5111 IC confers long-term protection against drug-induced disease and continues to protect mice even when control mice develop spontaneous disease." (PMID 36261022, 2022). "Moreover, a low dose of IL-2 administered in mice was able to prevent type 1 diabetes mellitus and improve the numbers of Tregs via their programming dependence on IL-2." (PMID 34685775, 2021). "Similarly, Treg depletion early in life by treatment with IL-2-neutralizing antibody results in early diabetes onset." (PMID 31281853, 2019). "IL-4 could inhibit IL-2-induced activation of NK and show anti-inflammatory roles based on its protective effects in diabetes." (PMID 30881587, 2019). "For instance, peroxisome proliferator-activated receptor-γ (PPAR-γ) activators: conjugated linoleic acid (CLA) and troglitazone inhibit free radical generation and TNF-α and IL-2 and, thus, inhibit the occurrence of diabetes in the Zucker diabetic fatty fa/fa rat." (PMID 28824543, 2017). "Indeed, transcriptional profiles of Tregs from individuals with recent-onset diabetes share many features with IL-2-starved, apoptosis-prone Tregs." (PMID 28770318, 2017). "The role of IL-2 in diabetes has been previously demonstrated." (PMID 24586872, 2014). "Furthermore, IL-2 administration has been shown to expand and activate Tregs in mice, while a short course of low-dose IL-2 administration at diabetes onset can reverse established disease." (PMID 24629100, 2014). "The inability of the expanded Treg cells to home in the damaged tissue might also lie behind the failure of an IL-2-based therapy for diabetes; indeed, supplementation with IL-2 further augmented the proliferative effects of rhIGF-1 on Tregs in vitro." (PMID 25339185, 2014). "Here, we describe that Ab/IL-2 immunotherapy treatment, given at the time of diabetes onset in NOD mice, not only correlated with reversal of diabetes and expansion of Treg cells, but also demonstrated the ability to significantly increase beta cell proliferation." (PMID 24205242, 2013). "In order to assess whether Ab/IL-2 immunotherapy still expanded Tregs in NOD mice with established diabetes, we analyzed spleen, pancreatic lymph node, and pancreatic lymphocytes by flow cytometry." (PMID 24205242, 2013).
diabetes (continued). "Moreover, studies have shown that treatment with exogenous IL-2 or Ab/IL-2 can selectively expand Tregs, improve immune regulation, and prevent or reverse disease at the onset of diabetes in NOD mice." (PMID 24205242, 2013). "An early study expanded Treg, isolated from an islet-specific TCR transgenic NOD mice (BDC2.5), with peptide pulsed DC and IL-2 and showed that these cells could prevent diabetes in prediabetic NOD mice." (PMID 24367363, 2013). "Therefore, we investigated expression of mature alpha and beta cell specific transcription factors in endocrine cells from pancreata of Ab/IL-2 treated NOD mice shortly after diabetes onset." (PMID 24205242, 2013). "In diabetes, the suppressed proliferation potential of diabetic T lymphocytes with mitogen stimulated was achieved by a decreased expression of adenosine kinase, and decreased IL-2 production by mitogen-stimulated diabetic T cells has been reported." (PMID 21716679, 2011). "Furthermore, treatment with IL-2 has been shown to induce Treg expansion and activation in humans and mice and protection against diabetes in NOD mice." (PMID 21647403, 2011). "Importantly, low-dose IL-2 treatment effectively attenuated retinal vasculopathy, with marked reductions in acellular capillaries (diabetes: 0.48-fold decrease, p<0.001), neovascularisation (OIR: 0.68-fold decrease, p<0.01) and vascular leakage, and expression of vascular endothelial growth factor." (PMID 40133487, 2025). "Therefore, a single infusion of autologous polyclonal Tregs and recombinant human low-dose IL-2 may be a novel treatment for diabetes." (PMID 36776877, 2023). "In order to establish whether the proportions of ILC3 and IL-2-expressing ILC3 change during the transition from prediabetes to diabetes, we assessed their frequencies along with Treg in the SILP in young (4 weeks of age) and mature (20 weeks of age) female NOD mice." (PMID 37110604, 2023). "Moreover, we showed that IL-2–tuned microbiota could be transplanted and protected IL-2–naive recipient mice against experimental inflammatory bowel disease and diabetes." (PMID 35917175, 2022). "Blocking interferons on their own does not prevent diabetes in knockout NOD mice, so we tested whether JAK inhibitor action on signaling downstream of common γ chain cytokines, including IL-2, IL-7 IL-15, and IL-21, may also affect the progression of diabetes in NOD mice." (PMID 33343569, 2020). "Thus, the spontaneously produced anti-IL-2 autoantibodies in young NOD mice could be used for predicting diabetes well before disease onset, either alone or in combination with IAA." (PMID 27708334, 2016). "Therefore, we developed a model of long-term diabetes to assess whether Ab/IL-2 immunotherapy could still have an impact via regeneration." (PMID 24205242, 2013). "It has been recently reported that insufficient IL-2 amounts in the pancreas are responsible for poor nTreg cell survival in this tissue, which could lead to progressive breakdown of self-tolerance and the development of diabetes in NOD mice." (PMID 21647403, 2011). "Thus, the decreased IL‐2 levels, potentially driven by changes in PRKG1, seen in individuals with diabetes and COVID‐19 may impair this immune mechanism, predisposing individuals with diabetes to worsened immune responses." (PMID 40476695, 2025). "Mouse models of streptozocin-induced diabetes and oxygen-induced retinopathy (OIR) were administered low-dose IL-2 (25,000 U) or vehicle (sterile water) by i.p. injection." (PMID 40133487, 2025). "Low-dose IL-2 significantly expanded CD4+CD25+Foxp3+ Tregs in the blood and spleen of mouse models of OIR and diabetes (1.4- to 1.9-fold increase, p<0.01)." (PMID 40133487, 2025). "Immunologically, type 1 diabetes mellitus patients showed significantly increased counts of T lymphocytes, CD3 + CD8 + T cells and B lymphocytes, along with decreased interleukin-2 and increased interleukin-6 levels compared to healthy controls." (PMID 41455069, 2025).
diabetes (continued). "Treatment with a low-dose IL-2/CD25 fusion protein has been reported to preserve beta cell function and prevent diabetes progression in mice." (PMID 40133487, 2025). "IL-2/CD25 fusion proteins are another exciting advancement that improved IL-2’s stability and function in delaying diabetes in animal models." (PMID 40804870, 2025). "Both ND and diabetes groups contained similar frequencies of TNF‐ and granzyme B‐producing CD8+ T cells, with IFNγ and IL‐2 production being significantly increased in T1D and T2D compared with ND, respectively." (PMID 41367201, 2025). "One notable study employed the administration of low-dose IL-2/CD25 fusion protein, forestalling diabetes onset and even managing overt diabetes in the NOD mouse model of T1D." (PMID 38507159, 2024). "Overexpressing CD73 with agents, such as AGT-5, Aire-overexpressing DCs, BAFFR-Fc, CD4+ peptide, ICAs, IL-2 therapies, SAgAs, sCD73, RAD51 inhibitor, TLR9 inhibitor, and VD decreases diabetes development." (PMID 39735551, 2024). "The upregulation of CD73 with agents, including AGT-5, Aire-overexpressing DCs, Aspirin, BAFFR-Fc, CD4+ peptide, ICAs, IL-2 therapies, SAgAs, sCD73, stem cells, RAD51 inhibitor, TLR9 inhibitor, and VD, decreased diabetes and atherosclerosis development." (PMID 39735551, 2024). "It is well established that CD4+CD25+ Tregs offer protection against diabetes in the NOD model, where they depend on IL-2 to exert their suppressive functions." (PMID 39704171, 2024). "The obtained findings show that the lower proportions of IL-2-expressing ILC3 and FoxP3+ Treg in SILP coincided with diabetes progression and severity." (PMID 37110604, 2023). "It was reported that children with one or two diabetes-related antibodies (IA-2 and/or GAD65) have significantly higher levels of IL-1β and IL-2 and lower levels of IL-4 than children with diabetes who were negative for these markers." (PMID 37893217, 2023). "Our data demonstrated that the serum proinflammatory cytokines IL-1β, TNF-α, IL-2, IFN-γ, and IL-4 and the anti-inflammatory cytokine IL-10 were dysregulated in diabetes and improved by OI intervention." (PMID 36918798, 2023). "The AUC, a measure of the diagnostic accuracy of risk factors for DGF, was 0.753, 0.655, 0.706 and 0.714 for donor terminal creatinine levels, a donor history of diabetes mellitus, CIT and donor IL-2 levels, respectively)." (PMID 35971094, 2022). "Univariate logistic analysis showed that donor terminal creatinine levels, donor history of hypertension, donor history of diabetes mellitus, CIT, and donor IL-2 levels were related to postoperative DGF." (PMID 35971094, 2022). "ELISA assays showed that the injection of tRF‐1020 mimics alleviated diabetes‐induced retinal inflammation as shown by decreased expression of VEGF, interleukin (IL)‐2, and TNF‐α." (PMID 36128646, 2022). "The AUCs were 0.817 for donor terminal creatinine levels, 0.625 for a donor history of diabetes mellitus, 0.769 for the CIT, and 0.819 for donor IL-2 levels." (PMID 35971094, 2022). "In the present study, we found that donor terminal creatinine levels, a donor history of diabetes mellitus, CIT and donor IL-2 levels were related to the occurrence of DGF." (PMID 35971094, 2022). "The AUCs were 0.753 for donor terminal creatinine levels, 0.655 for a donor history of diabetes mellitus, 0.706 for the CIT, and 0.714 for donor IL-2 levels." (PMID 35971094, 2022). "In this study, the serum levels of IL-2, IL-10, and INF-γ were higher in COVID-2019 patients with diabetes than both patients with IFG and patients with normal sugar." (PMID 33490288, 2021). "Two cytokine families that are important in diabetes pathogenesis are interferons (IFN), including type 1 IFNs and IFN-γ, and the common γ chain cytokines, including IL-2, IL-4, IL-7, IL-9, IL-15, and IL-21." (PMID 33343569, 2020).